BUB3 (BUB3 mitotic checkpoint protein)
Description:
Has a dual function in spindle-assembly checkpoint signaling and in promoting the establishment of correct kinetochore-microtubule (K-MT) attachments. Promotes the formation of stable end-on bipolar attachments. Necessary for kinetochore localization of BUB1. Regulates chromosome segregation during oocyte meiosis. The BUB1/BUB3 complex plays a role in the inhibition of anaphase-promoting complex or cyclosome (APC/C) when spindle-assembly checkpoint is activated and inhibits the ubiquitin ligase activity of APC/C by phosphorylating its activator CDC20. This complex can also phosphorylate MAD1L1.
Synonyms: BUB3L; hBUB3
Tractability: PROTAC: UniProt records ubiquitination sites on it; ubiquitination databases record sites on it; its protein half-life has been measured.
Gene: Protein-coding gene on chromosome 10 (123,154,395 to 123,170,467, forward strand). Ensembl gene ENSG00000154473.
Subcellular location: Nucleus; Chromosome, centromere, kinetochore
Subcellular location (Human Protein Atlas): Nucleoplasm
Pathways (Reactome):
Cell Cycle: APC-Cdc20 mediated degradation of Nek2A; APC/C:Cdc20 mediated degradation of mitotic proteins; Amplification of signal from unattached kinetochores via a MAD2 inhibitory signal; Cdc20:Phospho-APC/C mediated degradation of Cyclin A; EML4 and NUDC in mitotic spindle formation; Inactivation of APC/C via direct inhibition of the APC/C complex; Mitotic Prometaphase; Resolution of Sister Chromatid Cohesion; Separation of Sister Chromatids
Signal Transduction: RHO GTPases Activate Formins
Gene Ontology:
Molecular function: protein binding; ubiquitin binding
Biological process: attachment of spindle microtubules to kinetochore; protein localization to kinetochore; mitotic spindle assembly checkpoint signaling
Cellular component: kinetochore; mitotic checkpoint complex; nucleoplasm; bub1-bub3 complex; cytosol; nucleus
Genetic constraint (gnomAD): Loss-of-function variants: 22 observed, 40.79 expected, observed/expected ratio (o/e) 0.54, 90% interval 0.38 to 0.77. The upper end of that interval is the gene's LOEUF score, 0.77, which puts it in group 3 of 6, group 1 being the genes least tolerant of losing a copy. Missense variants: 303 observed, 432.02 expected, observed/expected ratio (o/e) 0.7, 90% interval 0.64 to 0.77. Synonymous variants: 168 observed, 163.18 expected, observed/expected ratio (o/e) 1.03, 90% interval 0.91 to 1.17.
Homologues: Orthologues: chimpanzee BUB3 (100% identical), pig BUB3 (100% identical), rabbit BUB3 (99% identical), guinea pig BUB3 (99% identical), mouse Bub3 (99% identical), dog BUB3 (99% identical), macaque BUB3 (99% identical), tropical clawed frog bub3 (90% identical), zebrafish bub3 (85% identical), rat Bub3 (67% identical), Drosophila melanogaster Bub3 (59% identical), Caenorhabditis elegans bub-3 (44% identical). Paralogues in human: RAE1 (35% identical), DNAAF10 (23% identical).
Diseases named in the same sentence as BUB3 in open-access papers:
BUB3 is named in the same sentence as 58 diseases in open-access papers, as found by Europe PMC text mining. Sharing a sentence is not in itself a finding about the gene and the disease. The quoted sentences say what the papers report.
breast carcinoma (15 papers, 2002 to 2024). "High expression of BUB1 and BUB3 in low-grade breast cancers was associated with longer overall survival." (PMID 36787437, 2023). "In other studies, however, high protein expression of BUB3 in low-grade breast cancers was associated with longer overall survival, whereas lower expression resulted in poorer outcomes." (PMID 35631670, 2022). "A previous analysis of the CGEM data reported only two genes, FGFR2 and BUB3, as risk factors for breast cancer." (PMID 29965997, 2018). "In low‐grade breast cancers, high expression rates of Bub3 protein was related to longer overall survival, while lower expression lead to poorer prognosis." (PMID 34882895, 2022). "The level of Bub3 protein and mRNA were overexpressed in the genetically unstable mammary cancer cell lines and high‐grade primary breast cancer tissues." (PMID 34882895, 2022). "In low‐grade breast cancers, high protein expression rates of Bub3 was related to longer overall survival, while lower protein expression lead to poorer prognosis." (PMID 34882895, 2022). "The BUB3’s importance was found in colorectal cancer at a young age and in low-grade breast cancers." (PMID 33841542, 2020). "For instance, genetic variation in the BUB3 gene did not affect familial breast cancer risk, and mutations in the BUB3 gene were shown to be rare in bladder tumors and glioblastomas." (PMID 35631670, 2022). "Upregulated BUB3 was also reported in breast cancer samples." (PMID 35631670, 2022). "They found that the mRNA and protein levels for Bub3 gene in the genetically unstable mammary cancer cell lines and high‐grade primary breast cancer tissues were significantly higher than that in the stable MCF‐10A and normal breast epithelial cells or in normal breast tissues." (PMID 34882895, 2022). "Interestingly, a majority of Survivin interacting molecules that were found to be significantly regulated by Pirfenidone are also associated with the mitotic spindle (MAD2L1, BUB1, BUB1B, BUB3, CDC20) and were shown to be increased in human breast cancer." (PMID 32039023, 2019). "So, Bub3 is speculated to be a potential marker for breast cancer." (PMID 34882895, 2022). "Breast cancers and breast cancer cell lines overexpress several mitotic regulators, including kinases that regulate the SAC such as Nek2, Mad1L1, Mad2L1, Mad2L2, BubR1, BubR1B, Bub3, Cdc20, and Mps1/TTK." (PMID 29100415, 2017). "Additionally, overexpression of BUB3, BUB1 and BUBR1 proteins has been reported in gastric cancer, clear cell kidney carcinomas and breast cancer." (PMID 24743044, 2014). "Besides, seven genes including BRCA1, FN1, CCNE1, CCND1, CHEK1, BUB3, and CDC25A were identified as the hub nodes by the PPI network, and CCNE1 and CHEK1 were confirmed to be related with the prognostic survival of the patients with breast cancer." (PMID 35186236, 2022).
colorectal cancer (10 papers, 2018 to 2024). A primary or metastatic malignant neoplasm that affects the colon or rectum. "Mutation in BUB3, an important member of spindle assembly checkpoint, leads to mosaic aneuploidy in affected individuals and a higher risk of colorectal cancer." (PMID 31030472, 2019). "Germline mutations in BUB1 and BUB3 have been reported to increase the risk of developing colorectal cancer (CRC) at young age, in presence of variegated aneuploidy and reminiscent dysmorphic traits of mosaic variegated aneuploidy syndrome." (PMID 29448935, 2018). "Moreover, the mutation or haploinsufficiency of BUB1 or BUB3 led to an increased risk of colorectal cancer at a young age." (PMID 36787437, 2023). "In addition, germline mutation of Bub3 is proposed to be a risk factor for colorectal cancer and pancreatic adenocarcinoma." (PMID 35085551, 2022). "Germline mutations in BUB1 and BUB3 are associated with an increased risk of colorectal cancer." (PMID 32596342, 2020). "Our results showed that YY2/BUB3 axis positively modulates SAC activity, prolongs mitotic time, and suppresses colorectal cancer (CRC) cells survival." (PMID 38682484, 2024).
lung cancer (8 papers, 2016 to 2025). A malignant neoplasm involving the lung. "The most significant APA alteration occurred in BUB3, which is part of the mitotic checkpoint pathway, a pathway containing genes that are commonly altered in selected lung cancers." (PMID 37487637, 2023). "The BUB3 gene has been found to be overexpressed in cases of gastric cancer, oral carcinoma, lung cancer, and prostate cancer." (PMID 36787437, 2023). "Overexpression of BUB3 was detected in oral cancer, gastric cancer, prostate cancer, and lung cancer." (PMID 33872216, 2021). "The role of BUB3 in the incidence and development of lung cancer has yet to be elucidated." (PMID 36787437, 2023). "But, more studies are needed to confirm the effect of Bub3 in lung cancer." (PMID 34882895, 2022). "BUB3 directly binds to LNC CRYBG3 and interrupts its interaction with CDC20 to result in aneuploidy, thus promoting the tumorigenesis and metastasis of lung cancer cells." (PMID 36787437, 2023). "Transcriptomic alterations that occur during lung cancer development include over-expressed cell cycle related genes like E2F3, BUB3, CDK4, MCM2, MCM3, and MCM7 as summarized by Powell and Borczuk." (PMID 26930711, 2016). "Moreover, USP7 appears to play a key role in lung cancers resistant to Paclitaxel through the regulation of two proteins involved in cell mitosis: Serine/threonine-protein kinase or polo-like kinase 1 (PLK1) and BUB3 Mitotic Checkpoint Protein (BUB3)." (PMID 41157055, 2025).
prostate carcinoma (8 papers, 2020 to 2024). A carcinoma that arises from epithelial cells of the prostate gland. "As better risk stratification of patients with prostate cancer is needed, we aimed to investigate whether the expression of BUB3, CCNB1 and PTTG1 could independently predict recurrence after radical prostatectomy." (PMID 31801961, 2020). "E2F4 is known to repress Bub3 and Pttg1, two important mitotic genes, in prostate cancer and play a crucial role in G2 arrest." (PMID 38173042, 2024). "Studies have demonstrated significant upregulation of BUB3 mRNA expression in prostate cancer compared to benign prostatic hyperplasia." (PMID 38825615, 2024). "The positive expression of cytoplasmic BUB3 protein was significantly related to the recurrence of prostate carcinomas." (PMID 36787437, 2023). "Protein levels were determined by immunohistochemistry and they found that cytoplasmic expression of Bub3 protein in 32% of their cases of prostate cancer." (PMID 34882895, 2022). "In prostate carcinomas, the positive expression of cytoplasmic Bub3 protein was significantly related to recurrence and the mRNA count of BuB3 in the nucleus was weakly related to protein level, neither were related to recurrence." (PMID 34882895, 2022). "The prognostic value of cytoplasmic BUB3 expression in prostate carcinomas has been reported for the first time in this study." (PMID 31801961, 2020). "Therefore, the prognostic value of Bub3 protein expression in the cytoplasm in prostate cancer suggests that whether Bub3 protein expression in the cytoplasm has the same or greater significance as other malignancies." (PMID 34882895, 2022). "The present study is the largest published study on the prognostic value of BUB3, CCNB1, and PTTG1 expression in prostate cancer." (PMID 31801961, 2020). "The mitotic checkpoint protein BUB3, cyclin B1 (CCNB1) and pituitary tumor-transforming 1 (PTTG1) regulates cell division, and are sparsely studied in prostate cancer." (PMID 31801961, 2020).
gastric cancer (7 papers, 2014 to 2024). A primary or metastatic malignant neoplasm involving the stomach. "They found that the level of Bub3 mRNA was overexpressed in 79% of gastric cancers and the high expression of Bub3 gene was also related to the high expression of Ki67 in GC." (PMID 34882895, 2022). "BUB3 was upregulated in 79% of gastric cancers, being a proliferation-dependent phenomenon in gastric cancer." (PMID 35631670, 2022). "Therefore, more studies on the regulation mechanism of Bub3 gene expression in gastric cancer are needed." (PMID 34882895, 2022). "Overexpression of BUB3 was reported in several cancers such as breast and gastric cancer." (PMID 28977903, 2017).
pancreatic cancer (6 papers, 2018 to 2024). "Subsequently, Bub3/DMAP1 interaction was examined in pancreatic cancer cell PANC-1 cells and SW1990 cells." (PMID 30553276, 2018). "Here, we show DMAP1/Bub3 complex mediates mitotic stress-induced cellular apoptosis, while this effect is counteracted by c-Src in pancreatic cancer cells." (PMID 30553276, 2018). "Our study delves into the intricacies of nab-paclitaxel resistance in a model of pancreatic adenocarcinoma, PANC-1, and pinpoints the pivotal role played by three SAC proteins—BUB1B, TTK, and BUB3—in determining sensitivity of a pancreatic cancer cell line to paclitaxel." (PMID 38410481, 2024). "DMAP1 was highly phosphorylated in pancreatic cancer cells, which impeded DMAP1/BUB3 interaction and the relevant cellular activity." (PMID 36787437, 2023). "Meanwhile, DMAP1 was highly phosphorylated at Tyr 246 by c-Src in pancreatic cancer cells, which impedes DMAP1/Bub3 interaction and the relevant cellular activites." (PMID 30553276, 2018). "Our findings reveal a regulatory role of Bub3 in DMAP1-mediated DNA methylation upon mitotic stress and provide the relevance of DMAP1 pTyr-246 to mitotic stress resistance during pancreatic cancer treatment." (PMID 30553276, 2018). "In pancreatic cancer cells, DMAP1 is highly phosphorylated by c-Src; this phosphorylation abrogates DMAP1/Bub3 complex formation under mitotic arrest and eventually maintains cell survival." (PMID 30553276, 2018). "In our study, we found pancreatic cancer cells display high level of DMAP1 pY246 mediated by c-Src; and this blocks mitotic arrest-induced Bub3/DMAP1 interaction and thus protects cancer cells from mitotic arrest-induced apoptosis." (PMID 30553276, 2018).
sarcoma (6 papers, 2021 to 2024). A usually aggressive malignant neoplasm of the soft tissue or bone. "Higher expression levels of BUB1, BUB1B, and BUB3 were found in sarcoma samples and were associated with lower overall and disease-free survival in sarcoma patients." (PMID 38473259, 2024). "BUB3 levels were reported to be higher in sarcoma samples, and higher expression levels of BUB3 were associated with lower overall and disease-free survival in patients with sarcomas." (PMID 35631670, 2022). "Survival analysis revealed that the higher expression levels of BUB1, BUB1B and BUB3 were associated with lower overall and disease-free survival in patients with sarcomas." (PMID 33872216, 2021). "This study implies that BUB1, BUB1B and BUB3 are potential treatment targets for patients with sarcomas and are new biomarkers for the prognosis of sarcomas." (PMID 33872216, 2021). "Despite the uncertain roles of BUB3 in cancers seen in previous studies, our study shows a positive correlation between BUB3 and human sarcomas, as well as sarcoma cell lines, especially in osteosarcoma, chondrosarcoma and Ewing sarcoma." (PMID 33872216, 2021). "We found that the expression levels of BUB1, BUB1B and BUB3 were higher in sarcoma samples and cell lines than in normal controls." (PMID 33872216, 2021). "BUB1, BUB1B, and BUB3 may serve as a future potential treatment targets and prognostic biomarkers for patients with sarcomas." (PMID 38473259, 2024). "Our results indicated that BUB1, BUB1B and BUB3 may serve as oncogenes in sarcomas and have significant prognostic values." (PMID 33872216, 2021). "Additionally, the expression level of BUB3 was significantly higher in cases of cervical, bladder, head, brain, colorectal, central nervous system, gastric, head, blood, and liver cancers, as well as melanomas and sarcomas." (PMID 36787437, 2023). "Three BUB family members have been identified in patients with different types of sarcoma: BUB1, BUB1B and BUB3." (PMID 33872216, 2021). "Additionally, in comparison to the normal controls, the sarcoma tissues and cells exhibited obviously high BUB1, BUB1B, and BUB3 expression." (PMID 36439516, 2022).
colon carcinoma (5 papers, 2006 to 2025). "The Western blot result showed that a higher (P < 0.01) expression of BUB3 protein was detected in these five colon cancer cell lines." (PMID 35156516, 2022). "The expression level of miR-664b-3p and Budding uninhibited by benzimidazole 3 (Bub3) in colon cancer cell lines and tissues were detected and analyzed using quantitative real-time PCR and bioinformatics method." (PMID 35156516, 2022). "Encouraged by the difference in the expression level of BUB3 protein between normal cells and colon cancer cells, we further investigated the function of BUB3 in the development of the cancer cells." (PMID 35156516, 2022). "In this study, we hypothesized that miR-664b-3p regulates the progression of colon cancer by inhibiting the expression of Bub3 protein." (PMID 35156516, 2022). "Taken together, miR-664b-3p could negatively regulate the expression of BUB3, which is closely related to the occurrence and development of colon cancer." (PMID 35156516, 2022). "The study indicated that miR-664b-3p plays a significant role in colon cancer and could regulate the progression of colon cancer tumor growth by suppressing the expression of BUB3 protein." (PMID 35156516, 2022). "HTLV-1 Tax acts on genes indirectly by binding several TFs, such as TCF3, ELK1, and MYC in colon cancer, as well as POLB, BUB3, and CDK4, according to the HTLV-1 infection signaling pathway." (PMID 39228892, 2024). "Conversely, we found that 6 genes involved in the mitotic spindle checkpoint (TTK, BUB1, BUB3, CDC20, MAD2L1, and BUB1B) are overexpressed in colon cancer specimens." (PMID 16919171, 2006). "Meanwhile, the BUB3 protein could also reverse the promotion effect of miR-664b-3p on the apoptosis of the HCT116 and DLD-1 while boosting the expression of Bcl-2 and inhibiting the production of Bax, caspase-3, and caspase-9 in colon cancer cells over-expressed of miR-664b-3p." (PMID 35156516, 2022).
glioblastoma (5 papers, 2011 to 2022). The most malignant astrocytic tumor (WHO grade IV). "Very recently, we showed that inhibition of BUB3 compromises glioblastoma cell proliferation, mainly through senescence induction rather than by apoptosis, suggesting that premature senescence can be a viable approach to restrain cancer propagation." (PMID 35631670, 2022). "We established that Msi1 levels affect the expression of Bub1, Bub1B, MADL1 and CDC20 and Bub3 is a direct target of Msi1 in glioblastoma cells." (PMID 33804958, 2021). "Bub3 gene was obviously overexpressed in glioblastomas (Grade IV) and its expression increased almost with grade, indicating that Bub3 might serve as a prognostic marker for gliomas." (PMID 34882895, 2022). "Moreover, the level of Bub3 Y207 phosphorylation correlated with histone H3-S10 phosphorylation in human glioblastoma specimens and with glioblastoma prognosis." (PMID 26376677, 2015).
oral cancer (4 papers, 2021 to 2023). "In the clinical setting, Bub3 is overexpressed in multiple cancers, and overexpression of Bub3 is associated with poor survival in patients with adrenocortical carcinoma and oral cancer." (PMID 35085551, 2022). "Bub3 has been found to be abnormally expressed in many human cancers, including oral cancer, Glioma tumors, colorectal cancer (CRC) and more." (PMID 34882895, 2022). "The immunohistochemical results showed strong nuclear Bub3 staining in both OLP and ISOC regions, suggesting that Bub3 may play a similar role in oral cancer and in precursor lesions as OLP." (PMID 34882895, 2022).
oral squamous cell carcinoma (4 papers, 2020 to 2024). "Overexpression of BUB3 was detected in oral squamous cell carcinoma and was associated with increased cellular proliferation." (PMID 36787437, 2023). "BUB3 expression is upregulated in oral squamous cell carcinoma patients." (PMID 32596342, 2020). "We have investigated the role of some SAC components (BUBR1, BUB3 and SPINDLY proteins) in canine oral squamous cell carcinoma (OSCC) by immunohistochemical analysis of 60 canine OSCCs." (PMID 36428310, 2022). "This study provides the first analysis of SAC-related proteins BUBR1, BUB3 and SPINDLY in canine oral squamous cell carcinoma, correlating them with clinical-pathological parameters and a prognosis profile." (PMID 36428310, 2022).